SCARNA14 (small Cajal body-specific RNA 14)
Synonyms: U100
Gene: Small Cajal body-specific RNA gene on chromosome 15 (66,347,207 to 66,347,342, reverse strand). Ensembl gene ENSG00000252712.
Gene Ontology:
Biological process: RNA processing
Cellular component: Cajal body; nucleolus
Homologues: Orthologues: macaque SCARNA14 (99% identical), mouse Gm24289 (93% identical), guinea pig SCARNA14 (93% identical), zebrafish SCARNA14 (63% identical).